EGFR (epidermal growth factor receptor)
Diseases named in the same sentence as EGFR in open-access papers (continued):
Sharing a sentence is not in itself a finding about the gene and the disease.
lung cancer (continued). "Therefore, it is important to understand new mechanisms of EGFR-TKI-acquired resistance to explore new approaches for lung cancer therapy in the future." (PMID 35163707, 2022). "Epidermal growth factor receptor tyrosine kinase inhibitors (EGFR TKIs) are standard of care for patients with EGFR mutation-positive non–small-cell lung cancer (NSCLC) with common mutations (Del19 or L858R); however, 7%-23% of NSCLC tumors harbor uncommon EGFR mutations." (PMID 35274704, 2022). "In addition, the EGFR tyrosine kinase inhibitor lapatinib regulated mTOR to promote ferroptosis in lung cancer cells." (PMID 35359830, 2022). "In an animal experiment, 3-week administration of procaine on the mice with lung cancer (50 mg/kg/day) could significantly reduce the expression of the EGFR and the tumor volume." (PMID 35966857, 2022). "NEDD4 was confirmed to mediate cell migration signaling of EGFR in lung cancer." (PMID 35090513, 2022). "Notably, more cases with higher AXL expression were found by IHC in EGFR tyrosine kinase inhibitor (EGFR TKI)-resistant lung cancer tissues." (PMID 36261437, 2022). "A study on the natural compound polyphyllin I pointed out that the regulation of IL‐6/STAT3 signalling EGFR‐TKI may reverse epithelial‐to‐mesenchymal transition and serve as a potential new way to overcome the EGFR‐TKI resistance in lung cancer." (PMID 35605028, 2022). "Lung cancer in non-smokers and tobacco-associated lung cancer seems to be two distinct entities owing to the strikingly different EGFR mutation status and clinicopathological features." (PMID 35497180, 2022). "To investigate the inhibitory effects of MA in lung cancer cells, we treated different types of lung cancer cells, including KRAS-mutated lung cancer cell lines A549 and H157 and EGFR-mutated lung cancer cell lines HCC827 and PC9, with different concentrations of MA for 48 and 72 h." (PMID 36712673, 2022). "Moreover, the fast progress of target therapies primarily in lung cancer involved certain oncogenic proteins, especially ALK and EGFR mutations." (PMID 35514980, 2022). "Although EGFR mutation has been reported in non-adenocarcinoma lung cancer, particularly in squamous cell carcinoma (SCC), the PFS of EGFR-TKIs for EGFR mutated lung SCC was shorter than the patients with EGFR mutated adenocarcinoma." (PMID 35205720, 2022). "We believe this unique case sheds light on the treatment management of hepatic ruptures and supports the high response rate seen with TKIs in EGFR-mutated lung cancers, regardless of the patient's performance status." (PMID 35433405, 2022). "Oat avenanthramides inhibited EGFR, suppressing lung cancer cell growth and migration." (PMID 36230714, 2022). "PROTAC 39 induced obvious degradation of mutant EGFR in lung cancer cells." (PMID 35702041, 2022). "Additionally, increased expression of miR-3182 was reported in mutant EGFR lung adenocarcinoma cell lines, compared to wild-type EGFR lung cancer cell lines." (PMID 35008424, 2022). "PTPN3 suppresses lung cancer cell proliferation and migration by counteracting Src-mediated disheveled-associated activator of morphogenesis 1 (DAAM1) activation and actin polymerization and by promoting EGFR endocytic degradation." (PMID 35957898, 2022). "In searching for genes differentially expressed in lung cancer cells with mutated EGFR, we performed microarray analyses comparing the mRNA expression profiles between H1299 NSCLC cells permanently transfected with wild-type or mutated EGFR." (PMID 35267664, 2022). "Although EGFR, KRAS, and ALK mutations are generally considered mutually exclusive in NSCLC, recent studies have shown that above oncogenic driver mutations can co-exist in a certain amount of lung cancers." (PMID 36376839, 2022). "In lung cancers, non-small cell lung cancer showed a better prognosis in tumors with lower STING expression, and STING-expressing tumors showed a significantly higher frequency of EGFR and KRAS mutations." (PMID 35882970, 2022).
lung cancer (continued). "For example, it promotes atg4b-mediated autophagy and attenuates sorafenib sensitivity in hepatocellular carcinoma cells; it regulates eIF4A3/MUC1/EGFR signalling and modulates the response of EGFR-mutant lung cancer to EGFR tyrosine kinase inhibitor resistance." (PMID 35359593, 2022). "Therefore, ncRNAs show potential as prognostic, predictive and therapeutic biomarkers for EGFR TKI-resistant lung cancer." (PMID 36139582, 2022). "Typically, EGFR-mut lung cancer cohorts tends to be young, Asian, and female." (PMID 35061724, 2022). "Our innovative discovery of inactivated ADSL-AICAR signaling in the DTPCs may direct a clinical study in lung cancer patients who receive EGFR TKIs and then undergo the DTP state transition in the future." (PMID 35840668, 2022). "Therefore, we also performed crosstalk analysis, which confirmed “mechanisms of resistance to EGFR inhibitors in lung cancer” among the top enriched pathways." (PMID 35351890, 2022). "the authors perform a retrospective cohort among patients with lung cancer receiving EGFR targeted therapy, with the objective of assessing whether TB affects the outcome of patients with NSCLC." (PMID 35140255, 2022). "Adopting this treatment strategy for EGFR-mutant lung cancer may prevent or delay EGFR inhibitor resistance and improve patient survival outcomes." (PMID 35326664, 2022). "Drug molecules that could target knockdown or knockout of LINC00460 may represent potential therapeutic strategy for overcoming EGFR TKIs resistance and consequently improve the prognosis of EGFR mutant lung cancer patients." (PMID 35209919, 2022). "At present, EGFR and its signal transduction pathway have been studied as therapeutic targets, and a series of reversible EGFR tyrosine kinase inhibitors have been used in the clinical treatment of lung cancer." (PMID 36188592, 2022). "Interestingly, we found that ARHGs with active copy number increase (e.g. MYC, EIF4EBP1, EGFR) and ARHGs with active copy number loss (e.g. ATG16L1, MTOR, ULK1) also showed high expression in lung cancer tissues." (PMID 35333893, 2022). "Both patient-related and tumor-related factors could affect the efficacy and survival of EGFR-TKI treatment in lung cancer patients." (PMID 36528578, 2022). "Exosomes derived from gefitinib-treated EGFR mutant lung cancer PC-9 cells could attenuate cisplatin response by increasing autophagy flux in the recipient cancer cells." (PMID 35465266, 2022). "Therefore, the combination of HH inhibitors and EGFR-TKIs provide a novel treatment strategy for advanced lung cancer patients." (PMID 35433472, 2022). "miR-34a inhibits progression of lung cancer via targeting EGFR, a cancer-drive gene." (PMID 35432725, 2022). "The degradation of ErbB2 and EGFR that play direct roles in the progression of breast and lung cancers are degraded by hTid-1 via the proteasomal pathway which is an important indicator as to why hTid-1 can act as a potential molecule of interest in the future to treat cancers." (PMID 35854300, 2022). "The mean survival time of patients without EGFR mutations was 1.77 years in the single lung cancer group and 2.78 years in the LCF group." (PMID 36233811, 2022). "Lung cancer is a heterogeneous disease and sensitivity to treatment is not the same for all EGFR mutations." (PMID 36727053, 2022). "Also, in a group of early stage primary lung cancer patients with potentially resectable tumors (stage I/II/IIIa, n = 173), 7 KRAS (G12/G13) mutations and 1 EGFR L858R mutation were detected." (PMID 36413862, 2022). "We wanted to investigate whether riskscore was superior to EGFR expression level as a better survival indicator for lung cancer." (PMID 36101742, 2022).
lung cancer (continued). "For instance, for treating EGFR-driven lung cancers, EGFR TKIs has been the first choice." (PMID 36505399, 2022). "Clinicogenomic validation of mutant RBM10 in EGFR-mutant lung cancer." (PMID 35579943, 2022). "Although no dietary patterns such as an alkaline diet have been introduced in the treatment management of patients with lung cancer, future clinical trials investigating whether patient diet affects EGFR TKI response would be of high interest." (PMID 35203491, 2022). "The prolongation of mPFS in the non-EGFR/ALK group could be related to the fact that EGFR-mutant lung cancer patients had prior targeted therapy and therefore, worse performance status and more tumor burden at start of chemoIO therapy." (PMID 35884533, 2022). "Moreover, the ND-conjugated specific EGFR antibody cetuximab (Cet) can track the location and distribution of EGFR proteins of lung cancer cells in vitro and in vivo." (PMID 36678740, 2022). "In contrast, EGFR TKIs were approved for the treatment of EGFR-mutant lung cancer." (PMID 35922812, 2022). "This is in line with lung cancer data where AXL inhibitors could enhance the effect of EGFR-targeted therapies in resistant AXLhigh cells." (PMID 35332208, 2022). "Lung cancer patients with high programmed cell death-ligand 1 (PD-L1) expression in tumor cells and epidermal growth factor receptor (EGFR) mutations are rare, but there is no clinical standard for which treatment such patients should receive." (PMID 35898897, 2022). "Care must also be taken when interpreting ctDNA analysis which may not capture features such as histologic transformation, as seen in osimertinib resistance of EGFR mutant lung cancer with transformation to small-cell or squamous pathology." (PMID 35347327, 2022). "Results from multiple studies in lung cancer suggest that epithelial phenotype with increased ECAD gene (CDH1) or protein expression, as opposed to mesenchymal or EMT phenotype, is associated with increased sensitivity to EGFR inhibitors." (PMID 34890102, 2022). "Moreover, the L-scores of lung cancer cell lines were correlated with their sensitivity to targeted drugs such as EGFR inhibitors." (PMID 35016696, 2022). "For 34 indications (24.1%), a drug’s lack of a statistically significant OS benefit was documented before approval (except for osimertinib for second-line therapy in epidermal growth factor receptor T790M–positive advanced non–small cell lung cancer, for which OS data matured after approval)." (PMID 35947385, 2022). "EGFR plays a relevant biologic role in the process of lung cancer development and progression." (PMID 35346313, 2022). "A study fully illustrated the role of Hh signaling in EGFR mutant lung cancer, their result showed that, through the induction of mesenchymal properties, Hh could mediate the resistance of EGFR inhibitors." (PMID 36619616, 2022). "Additionally, one whole-genome sequencing study analyzing several EGFR-mutant lung cancers transforming into small cell lung cancer after an initial response to EGFR-TKI demonstrated that small cell lung cancer precursors were already present before treatment." (PMID 35326664, 2022). "According to the study focusing on the role of METTL3 in lung adenocarcinoma, METTL3 could enhance mRNA translation including EGFR and Hippo pathways, further promoting growth and invasion of human lung cancer cells." (PMID 35860263, 2022). "This EGFR response has been shown to be exhibited in up to 50% of lung cancer patients." (PMID 36085575, 2022).
lung cancer (continued). "Regarding the clinicopathological aspects, HER2 mutations in lung cancer are significantly associated with female sex, never smoking, and an adenocarcinoma histological subtype, such as that observed in EGFR-mutated NSCLC patients." (PMID 36294789, 2022). "However, although EGFR-TKIs such as gefitinib and erlotinib de novo show favorable response to EGFR mutant lung cancer, the resistance to EGFR-TKI is eventually inevitable." (PMID 35664735, 2022). "But, on the contrary, treatments like checkpoint inhibitors or even drugs like osimertinib in Epidermal Growth Factor Receptor (EGFR) mutated lung cancer are not commonly supported." (PMID 36819818, 2022). "More importantly, testing AhR expression or Kyn level might help to predict the EGFR TKIs responses in lung cancer." (PMID 35831824, 2022). "The importance of EGFR in lung cancers supports the concept of “oncogene addiction”." (PMID 35053080, 2022). "All these findings show that in the future, this selected compound may have better anticancer properties for EGFR-targeted treatment in breast cancer and lung cancer." (PMID 36457709, 2022). "Studies have shown that the ZDHHC20 expression was elevated in breast and lung cancer cell lines in which epidermal growth factor receptor (EGFR) signaling is present, which implied that ZDHHC20 might play a key role in signal regulation during oncogenesis." (PMID 36286021, 2022). "A relationship between chromothripsis and the EGFR driver mutation in lung cancers has not been well-characterized." (PMID 35710642, 2022). "Therefore, a close correlation between the metabolic activity of lung cancer on 18F-FDG PET/CT and EGFR mutations was formed naturally." (PMID 35497180, 2022). "EGFR-mutant lung cancer, for instance, is more prevalent in Asia than in North America." (PMID 35847783, 2022). "For Asian patients with lung cancer, EGFR mutant NSCLC is the most prevalent subtype." (PMID 36619616, 2022). "This is an interesting clinical finding that can further the exploration of the mechanism behind elevated EGFR expression in patients with primary breast cancer and the mechanism of EGFR expression in lung cancer and breast cancer, paving the way for development of new drugs." (PMID 36313724, 2022). "For example, miRNA-138-5p was significantly down-regulated in lung cancer cells resistant to gefitinib (a widely used small molecule EGFR tyrosine kinase inhibitor); re-expression of miRNA-138-5p was sufficient to sensitize gefitinib-resistant lung cancer cells to gefitinib." (PMID 36497250, 2022). "Historically, ex19del mutations have not been differentiated in the clinic, and despite the known heterogeneity within this cohort of EGFR-mutant lung cancer, variant-specific differences in ex19del have not been widely considered." (PMID 35867821, 2022). "A phase II clinical study showed that osimertinib plus bevacizumab is beneficial in the treatment of lung cancer brain metastases, and our previous study indicated that osimertinib plus bevacizumab was safe and effective for the treatment of LM in EGFR-mutant lung cancer [NCT04148898]." (PMID 35287683, 2022). "Notably, NOP56 silencing also inhibited NRAS-mutant lung cancer H1299 cells, although the effects on EGFR-mutant (EBC-1) or FGFR1-amplified (H520) lung cancer cells were negligible." (PMID 35039048, 2022). "In the current study, we did not detect any EGFR germline mutations in the 1794 lung cancer patients." (PMID 35273153, 2022). "Interestingly, we found that lung cancer cohorts with genetic alterations of EGFR, MAP2K1, mTOR, TEAD1, and YAP1 exhibited worse prognoses of overall, disease-specific, and progression-free survival compared to patients with wild-type (WT) genes." (PMID 35655775, 2022). "EGFR or ALK gene status is included in the amendment of lung cancer score, lung-molGPA." (PMID 35558520, 2022). "This might imply that lung cancer patients ineligible for treatment with ICIs or EGFR TKIs might benefit from ADAMTS8 treatment." (PMID 35743687, 2022).
lung cancer (continued). "We reasoned that loss-of-function genetic alterations in RBM10 that dampen the apoptotic response to EGFR inhibitor therapy could enhance cancer cell survival in patients with EGFR-mutant lung cancer." (PMID 35579943, 2022). "Furthermore, the role of EGFR in lung cancer is better established as it is already a targeted therapy." (PMID 35053080, 2022). "In addition, the metabolic pathway of arachidonic acid is linked to the biological basis of lung cancer due to the involvement of biosynthetic cyclooxygenases (COX-2) and phospholipase A2 (PLA2) in the MAPK/ERK and EGFR pathways." (PMID 36142846, 2022). "An additional four plasma specimens from patients with EGFR-mutated lung cancers showed mutant events in replicate reactions but did not meet the criteria for reporting (at least 3 events in each replicate reaction)." (PMID 35202431, 2022). "Mutant EGFR lung cancer could upregulate SEMA7A/ITBG1 axis, which normally activates ERK signaling and leads to apoptosis resistance." (PMID 36619616, 2022). "Indeed, in ctDNA-positive lung cancer samples, the detection rate of EGFR alterations was 62.8%, with more than a third of detected EGFR alterations being in-frame exon 19 deletions." (PMID 35486650, 2022). "We have shown that EVs conjugated with a peptide or a single domain antibody targeting EGFR promote the specific uptake of EVs by EGFR‐positive lung cancer cells, thereby enhancing the delivery of paclitaxel to lung tumours for better treatment of lung cancer." (PMID 35851970, 2022). "Known ALK/ROS1 fusions and 5′‐/3′‐end unbalanced expression were analyzed in 2009 EGFR mutation‐negative non‐small cell lung cancer (NSCLC) samples with RT‐PCR tests, which were optimized for the use with FFPE‐derived RNA." (PMID 35322575, 2022). "We therefore tested whether CrT/TICs secrete EGF to activate EGFR signalling in differentiated lung cancer cells." (PMID 36504325, 2022). "Interestingly, Ras/Raf/MAPK and PI3K/AKT, two major signaling pathways downstream of EGFR, can promote mitosis and prevent apoptosis in lung cancer cells." (PMID 36232998, 2022). "EGFR is associated with EMT and metastasis in many tumors, including lung cancer." (PMID 36080307, 2022). "Molecular profiling of lung cancer samples for activated oncogenes, including epidermal growth factor receptor (EGFR), anaplastic lymphoma kinase (ALK) and c–ros oncogene 1 (ROS1), is considered as standard-of care to select the most appropriate up-front treatment." (PMID 36551608, 2022). "Another interesting finding was the lack of association between P/LP germline mutations and EGFR mutations, which are well documented to be far more prevalent in Asian lung cancer patients than western populations." (PMID 35273153, 2022). "Epidermal growth factor receptor (EGFR) mutations are more commonly reported in lung adenocarcinoma and in female patients of East-Asian origin, which directs to the importance of estrogen signaling in lung cancer." (PMID 35664735, 2022). "It was revealed in a study that unlike the mutation of EGFR in the case of lung cancer, the progression of TNBC is related to an increased number of EGFR genes, and not the mutation of EGFR." (PMID 35631368, 2022). "This study described a novel mechanism of EGFR TKIs resistance development in lung cancer." (PMID 35831824, 2022). "Furthermore, combination of A3 with EGFR TKIs synergistically affected cell proliferation and inhibited tumor growth in lung cancer xenografts, including gefitinib-resistant models." (PMID 36271429, 2022). "In vitro, we experimentally demonstrated that the combination of an IDH inhibitor and EGFR TKI could better inhibit lung cancer cell proliferation than an EGFR TKI alone." (PMID 35526267, 2022). "However, further experimental studies are required to fully elucidate the role of YAP/EGFR in lung cancer metastasis." (PMID 35655775, 2022).